S100A9 (S100 calcium binding protein A9)
Diseases named in the same sentence as S100A9 in open-access papers (continued):
Sharing a sentence is not in itself a finding about the gene and the disease.
polyarticular JIA (1 paper, 2025). "Similarly, in patients with SoJIA, the serum levels of S100A8 and S100A9 are notably elevated, with a 12-fold increase in active polyarticular JIA patients and a striking 120-fold increase compared to normal controls." (PMID 39877611, 2025).
polyp (1 paper, 2020). A usually exophytic mass attached to the underlying tissue by a broad base or a thin stalk. "When the correlation between the clinical data and gene expression was studied, a positive correlation between the expression of S100A9 and the size of the lesion in adjacent but not polyp tissue was found (p = 0.0043, r = −0.515)." (PMID 32325745, 2020).
psoriasis vulgaris (1 paper, 2016). Plaque psoriasis is the most common presentation of psoriasis. "For immunohistochemistry of calprotectin, a skin specimen from a patient with psoriasis vulgaris was used as a positive control, because S100A8 and S100A9 are up-regulated in psoriatic epidermis." (PMID 27442430, 2016).
psychological distress (1 paper, 2024). "In addition, monitoring S100A8/S100A9 levels could lead to earlier intervention in managing psychological distress in metastatic patients, which was linked to increased inflammatory signaling." (PMID 39830522, 2024).
pyometra (1 paper, 2015). "Thus, high levels of S100A8 and S100A9 in pyometra may be a result of tissue damage leading to amplification and/or perpetuation of the local inflammation, being an attractive therapeutic target." (PMID 26222498, 2015). "Overexpression of S100A8, S100A9 and S100A12 genes were detected in pyometra, particularly in the hormone-treated animals." (PMID 26222498, 2015). "SLPI, PTGS2/COX2, MMP1, S100A8, S100A9 and IL8 were among the top up-regulated genes detected in pyometra, further confirmed by external expression data." (PMID 26222498, 2015).
rectal cancer (1 paper, 2024). A primary or metastatic malignant neoplasm that affects the rectum. "Specifically, S100A9 was the target of five drugs, of which calcium has been approved by the FDA for the treatment of colon and rectal cancers." (PMID 39175079, 2024). "Take S100A9 as an example, S100A9 was the target of five drugs, of which the FDA has approved calcium for the treatment of colon and rectal cancers." (PMID 39175079, 2024).
renal carcinoma (1 paper, 2011). A carcinoma arising from the epithelium of the renal parenchyma or the renal pelvis. "If this could be confirmed in a renal cancer model, S100-A9 would be a promising target to study tumor progression." (PMID 21760917, 2011).
renal dysfunction (1 paper, 2024). "Specifically, S100-A9 and CatB were indicators of preoperative renal dysfunction in septic patients." (PMID 39049003, 2024).
Respiratory tract infection (1 paper, 2025). An infection of the upper or lower respiratory tract. "However, there was no statistical difference in S100A9 levels was observed between septic patients with respiratory tract infection and those without." (PMID 40478888, 2025).
retinoblastoma (1 paper, 2025). A malignant tumor that originates in the nuclear layer of the retina. "Among the most upregulated genes were KRT5, KRT19, LCN2, SLP1 and S100A9, while GNAT1, PDE6G, WIF1, FRZB, and RHO were among the top downregulated genes in retinoblastoma." (PMID 40395327, 2025).
rosacea (1 paper, 2025). A chronic erythematous skin disorder that affects the face. "Therefore, TLR2 and S100A9 may be associated with the observed skin thickening and accelerated damage repair processes in rosacea." (PMID 39823143, 2025). "Our findings also reveal a significant upregulation of TLR2 and S100A9 expression in rosacea patients, which is consistent with previous research on TLR2 and S100A9." (PMID 39823143, 2025). "The upregulation of TLR2 and S100A9 may promote the pathogenesis of rosacea and inflammatory reaction." (PMID 39823143, 2025). "Thus, TLR2 and S100A9 play important roles in the inflammatory reactions and immune regulation of rosacea." (PMID 39823143, 2025). "In in vitro experiments, the study found that TLR2 and S100A9 protein levels increased in HaCaT cells under conditions simulating rosacea, and the cytokines IL6, OSM, and TNF‐α were significantly elevated, implying their potential promoting roles in the progression of rosacea." (PMID 39823143, 2025). "Compared with the healthy control group, the rosacea patient group showed significantly increased mRNA and protein levels of TLR2 and S100A9." (PMID 39823143, 2025). "To elucidate the pivotal roles of TLR2 and S100A9 in the pathogenesis of rosacea, we established knockdown cell lines for TLR2 and S100A9." (PMID 39823143, 2025).
salivary gland tumors (1 paper, 2024). "Some of the identified peptides were derived from proteins previously suggested as potential biomarkers of salivary gland tumors (ANXA1, BPIFA2, FGB, GAPDH, HSPB1, IGHG1, VIM) or tumors of other tissues or organs (SERPINA1, APOA2, CSTB, GSTP1, S100A8, S100A9, TPI1)." (PMID 39201484, 2024).
scleroderma (1 paper, 2023). Scleroderma is a rare autoimmune connective tissue disorder characterized by abnormal hardening of the skin and, sometimes, other organs. "Furthermore, S100A9 exacerbated skin fibrosis and increased the expression of ERK1/2 MAPK signalling pathways in scleroderma." (PMID 37936894, 2023).
scrapie (1 paper, 2020). A fatal disease of the nervous system in sheep and goats, characterized by pruritus, debility, and locomotor incoordination. "In the current study, none of the target genes (GFAP, SAA3, CXCL10, CD14, S100A9, and IL1B) associated with the acute phase response and inflammation were differentially expressed in the hippocampus of animals with and without scrapie." (PMID 31924264, 2020).
Senile plaques (1 paper, 2019). Senile plaques are extracellular deposits of amyloid in the gray matter of the brain. "Growing evidence supports the protective role of senile plaques in local inflammation driven by S100A9." (PMID 30794655, 2019).
severe acute respiratory syndrome (1 paper, 2009). A viral respiratory infection caused by the SARS coronavirus. "Interestingly, S100A9 and S100A12 have been reported to be up-regulated in peripheral blood mononuclear cells (PBMCs) during severe acute respiratory syndrome (SARS)." (PMID 19196461, 2009).
thoracic aortic aneurysm (1 paper, 2024). An aneurysm formed in the wall of the proximal portion of the descending aorta proceeding from the arch of the aorta. "Many S100 family proteins, such as S100A8, S100A9, and S100A12, play a key role in thoracic aortic aneurysms and other cardiovascular diseases 40-42." (PMID 38164183, 2024).
tularemia (1 paper, 2016). Tularemia is an infection caused by the bacterium Francisella tularensis. "Later in pulmonary tularemia, the release of inflammatory cytokines (IL-1β, IL-6, TNFα, etc.)and DAMPs/alarmins (e.g. HMGB1, S100A9) are suggested ‘drivers’ of host death." (PMID 27015566, 2016).
typhoid fever (1 paper, 2015). A bacterial infectious disorder contracted by consumption of food or drink contaminated with Salmonella typhi. "In this study we aimed to characterize the expression and function of S100A8/A9 in typhoid fever, linking observational studies in patients with functional studies in S100A9-/- mice." (PMID 25860480, 2015).
Ureteral obstruction (1 paper, 2022). Obstruction of the flow of urine through the ureter. "Further, in an experimental unilateral ureteral obstruction (UUO) model, S100A9 knockout mice, which are deficient in S100A9 and S100A8, are protected from renal damage and fibrosis compared to wild-type mice." (PMID 36017003, 2022).
urticaria (1 paper, 2025). A vascular reaction of the skin characterized by erythema and wheal formation due to localized increase of vascular permeability. "S100A7, S100A8, S100A9, S100A12, IL6 and SOCS3, whose mRNA expression correlated positively with the urticaria activity score and may have a potential diagnostic value." (PMID 40635160, 2025).
uterine cancer (1 paper, 2023). Primary or metastatic malignant neoplasm involving the uterine corpus and/or the cervix. "Notably, analysis of TCGA Pan-Cancer Atlas showed a consistent positive correlation between SERPINB3 and CXCL1, CXCL8, S100A8, and S100A9 across multiple tumor types including bladder, breast, head and neck, lung, prostate, and uterine cancers." (PMID 37279067, 2023).
vaginal infections (1 paper, 2024). "Researchers have further elucidated the biological role of S100 alert proteins in the pathogenesis of C. albicans vaginal infections, observing that antibody neutralization of S100A8 and S100A9 affects the chemotactic activity of neutrophil in vaginal lavage." (PMID 38794163, 2024).
viral meningitis (1 paper, 2025). Inflammation of the membranes surrounding the brain and spinal cord due to a viral infection. "In contrast, patients with viral meningitis have a plasma protein profile dominated by acute-phase and pro-inflammatory markers (e.g., CRP, S100A8, S100A9) and immunoglobulin production." (PMID 41145505, 2025). "Notably, viral meningitis exhibited a different pattern, with both plasma and CSF showing elevated acute-phase reactants (e.g., CRP, S100A9) and immunoglobulins, consistent with a strong inflammatory and humoral response." (PMID 41145505, 2025).
viral pneumonia (1 paper, 2023). Inflammation of the lung parenchyma that is caused by a viral infection. "Finally, S100A9 appears to be a promising biomarker to distinguish bacterial from viral pneumonia patients." (PMID 37467233, 2023). "Moreover, S100A9 appears to be a promising biomarker to distinguish patients with bacterial from those with viral pneumonia." (PMID 37467233, 2023). "Moreover, S100A9 appears to be a promising biomarker to distinguish bacterial from viral pneumonia." (PMID 37467233, 2023). "We show that S100A9 was significantly increased in BAL fluids of patients with bacterial but not viral pneumonia and correlated with procalcitonin and sequential organ failure assessment scores." (PMID 37467233, 2023). "Capitalizing on these findings, we show that levels of S100A9 were significantly increased in BALF of patients with bacterial (including pneumococcal) but not viral pneumonia and positively correlated with CRP, PCT and SOFA scores." (PMID 37467233, 2023). "Moreover, S100A9 protein levels were positively correlated with C reactive protein (CRP) in BALF of patients with bacterial but not viral pneumonia (Pearson’s r = 0.54, p-value = 0.03 for bacterial versus viral pneumonia with Pearson’s r = -0.76, p-value = 0.01)." (PMID 37467233, 2023).
vulvovaginal candidiasis (1 paper, 2020). Infection of the vulva and vagina with a fungus of the genus CANDIDA. "During vulvovaginal candidiasis, IL-22-deficient mice also showed pronounced neutrophil recruitment to the vaginal epithelium, followed by increased production of AMPs, such as S100A8 and S100A9, as well as elevated tissue damage." (PMID 32517114, 2020).
tumor (528 papers, 2005 to 2026). "Previous studies have demonstrated that S100A9 is upregulated in various cancers and is closely associated with tumor initiation, progression and prognosis." (PMID 40296873, 2025). "For instance, increased expression of S100A8 and S100A9 is associated with pro-inflammatory signaling and enhanced tumor cell migration." (PMID 41404073, 2025). "Under pathological conditions, S100A9 is secreted by necrotic or immune-activated cells and plays a crucial role in the chemotaxis and infiltration of monocytes, TAMs, and tumor-associated neutrophils (TANs) in the tumor region." (PMID 39744679, 2025). "Calprotectin, a heterodimer composed of the S100A8 and S100A9 proteins, has been increasingly recognized as a key player in tumor-associated inflammation." (PMID 40869349, 2025). "In EC, multiple S100 proteins, including S100A1, S100A2, S100A4, S100A8, and S100A9, have been implicated in tumor proliferation, invasion, epithelial–mesenchymal transition (EMT), and response to chemotherapy." (PMID 41303754, 2025). "Our analysis of human SCLC patient samples showed that higher S100A9 expression in the tumor was linked to lower overall survival." (PMID 41173834, 2025). "Multiple S100 proteins, including S100A2, S100A4, S100A8, and S100A9, are significantly upregulated in EC compared with those in the normal endometrium, and their expression has been linked to tumor proliferation, invasion, and progression." (PMID 41303754, 2025). "Previous studies have reported that the overexpressed S100A8/S100A9 in tumor tissues is closely related to tumor‐associated inflammation, epithelial–mesenchymal transition, and metastasis, contributing to poor prognosis." (PMID 38962427, 2024). "S100A7 and S100A9 also contribute to oxidative stress, recruitment of tumor-associated macrophages (TAMs), and pro-angiogenic signaling." (PMID 39830522, 2024). "Functional enrichment analysis and volcano plots pinpointed the Ma_1 cluster’s enrichment in pathways pertinent to hypoxia and epithelial-mesenchymal transition, categorizing this subgroup as S100A9 Ma, linked to tumor advancement." (PMID 39136841, 2024). "In our experiments, early inhibition of S100A9 with Paquinimod caused decrease in overall immune cell infiltration to tumors in CT26 mouse tumor model." (PMID 39497822, 2024). "Recent studies have also shown that upregulated S100A8 and S100A9 and their associated inflammatory factors were presented in the tumor microenvironment since the inflammation conditions are strongly involved in the neoplastic process and cancer development." (PMID 39575241, 2024). "A particular focus was placed on a pro-tumor macrophage cluster marked by S100A9, which is implicated in promoting angiogenesis and tumor advancement through its interactions with endothelial cells." (PMID 39136841, 2024). "S100A8 and its cognate-binding partner S100A9 exhibit potential prognostic biomarkers for reactivation of dormant tumor cells, prediction of metastatic risk and therapeutic responses failure in several malignancies, including BC." (PMID 39830522, 2024). "We also found that LYPD3 was co-expressed with S100A9 and associated with immunosuppressive tumor microenvironment (TME)." (PMID 37924160, 2023). "Increased expression of S100A9 protein in the serum has been previously associated with tumor grade." (PMID 37016361, 2023). "S100A9 is a secreted protein associated with an inflammatory microenvironment, and its expression in tumor tissues is associated with poor survival in HCC patients." (PMID 37171396, 2023). "Cells treated with high concentrations of S100a9 caused apoptosis, and low concentrations caused tumor invasion." (PMID 36810783, 2023). "Consistent with this concept, S100A9 is strongly expressed by tumor-associated macrophages in the liver." (PMID 36232334, 2022). "The protein complex S100A8/S100A9 is an important promoter of tumor invasiveness and has been associated with poor prognosis." (PMID 33401528, 2021).
tumor (continued). "Inflammatory mediator S100A9 was secreted as a damage-associated molecular pattern (DAMP) in the tumor microenvironment (TME) of many inflammatory tumors, including gastric cancer, prostate cancer, and liver cancer." (PMID 34093546, 2021). "S100A9 is a calcium‐binding protein implicated in tumor metastasis, progression, and aggressiveness that modulates the tumor microenvironment into an immunosuppressive state." (PMID 34519180, 2021). "Using digital spatial profiling, it was also recently shown that after intratumoral injection of STING-activating nanoparticles, the expression of B7-H3 and S100A9 immune checkpoints, which are associated with tumor immune evasion is increased." (PMID 34070756, 2021). "For example, elevated S100A9 in malignant tissues were associated with significantly shorter cancer survival, while downregulated S100A9 is correlated with tumor proliferation, inflammation invasion and angiogenesis." (PMID 34689294, 2021). "S100A8 and S100A9 have been implicated in inflammation and tumor development, exerting a complex and multifactorial role." (PMID 32733643, 2020). "While PRDX3 down-regulation was associated with increasing tumor stage, S100A9 and PHB increased in abundance and were also associated with tumor grade." (PMID 32742246, 2020). "Further, increased GM-CSF was associated with higher T stage, and CD33+S100a9+ cell infiltration was associated with higher tumour grade and less differentiated tumours." (PMID 32747748, 2020). "S100A4 and S100A9 show common molecular interactions, both being associated with inflammation and in vivo tumor progression, reducing overall survival for the patient." (PMID 32290283, 2020). "Many studies have shown that intracellular S100A9 activates several tumor-associated signaling pathways and upgrades the proliferation of tumor cells." (PMID 33203795, 2020). "Proteomic studies in blood serum of patients with BC revealed Calprotectin–the heterodimer of the proteins S100A8 and S100A9 –as a tumour-associated protein that is linked to bladder wall muscle invasion of the tumour as well as cancer-specific survival." (PMID 30870488, 2019). "In this study, we investigated the association between MDSCs and S100A9 in CRC tumor tissues and peripheral blood, and the effect of molecular mechanisms of S100A9 on trafficking, cell vitality, and activation of MDSCs in CRC." (PMID 31620141, 2019). "No such relationship was observed for S100A9-positive monocytes, indicating a distinction between S100A8- and S100A9-expressing tumour-associated monocytes." (PMID 30558665, 2018). "The protein heterodimer of S100A8 and S100A9 has been implicated in tumor development and progression." (PMID 29607329, 2018). "The calcium binding protein S100A9, associated with loss of differentiation and recurrence, tends to be deregulated in both tumour and stromal cells." (PMID 28381274, 2017). "S100A9 has, however, also been implicated in tumor development as it was shown to be important for the accumulation of suppressive myeloid cells and the negative regulation of the maturation of these cells to dendritic cells." (PMID 27400708, 2016). "S100A9 expression has previously been associated with ER−PR− tumours, both when expressed in the myeloid cells but also in the malignant cells per se21." (PMID 27725631, 2016). "Through TCGA analysis, it was determined that the mRNA levels of S100A8 and S100A9 genes were associated with RCC tumor T stage, which demonstrated that a higher expression indicated a higher stage." (PMID 25673070, 2015). "Elevated expression of MMP-3, Pthlh and S100a8 was confirmed in isolated primary tumour epithelial cells of the two metastatic variants, as was expression of S100a9, a binding partner for S100a8." (PMID 25633981, 2015). "Instead, CD34+ vessel number was positively associated with the presence of CD68 in tumor stroma, furthering the notion that S100A9 promotes angiogenesis in vivo through increased macrophage recruitment." (PMID 26315114, 2015).